ENSG00000212458
Synonyms: LOC124900184
Gene: Small nucleolar RNA gene on chromosome 4 (1,118,884 to 1,119,013, forward strand). Ensembl gene ENSG00000212458.
Gene Ontology:
Biological process: RNA processing
Cellular component: nucleolus
Homologues: Paralogues in human: SNORA48 (89% identical), SNORA48B (89% identical).